SCP2 (sterol carrier protein 2)
Diseases named in the same sentence as SCP2 in open-access papers (continued):
Sharing a sentence is not in itself a finding about the gene and the disease.
viral infection (1 paper, 2022). "Interestingly, we found that the ubiquitination of many host proteins that interact with SARS-CoV-2 was also changed after viral infection, such as ZDHHC5, BUD31, SCP2, ARL6IP4, and NUDCD2, which were reported to interact with the SARS-CoV-2 Spike protein." (PMID 36071039, 2022).
tumor (20 papers, 2010 to 2025). "Correlation analysis with tumor-associated fibroblasts showed that Egr1 + FibC1 and Scp2 + Fib-C2 were highly correlated with pan-iCAF-2 and pan-pCAF, respectively." (PMID 38753279, 2024). "A recent study demonstrated acquired SCP2:NTRK1 fusions associated with tumor progression on tamoxifen and letrozole treatment." (PMID 39038933, 2024). "The genes EZH2 was significantly higher expressed in tumor tissue while SCP2, ALDH3A2, and PRKAA2 were significantly upregulated in normal tissue." (PMID 40271062, 2025). "SCP2-specific inhibitors are known to induce autophagy in tumor cells by inhibiting the AKT1-mTOR signaling pathway, thereby suppressing tumor cell proliferation." (PMID 38406279, 2024). "We constructed a stably transfected PC cell line PANC‐1 expressing oe‐LINC00261, sh‐LINC00261, oe‐FOXP3, sh‐SCP2 or Vector and subcutaneously injected into a tumour model in mice." (PMID 34541823, 2021). "In our study, we initially found that SCP2 expression was higher in human PA samples than the normal pituitary gland and was positively correlated with tumor proliferative activity." (PMID 31519191, 2019). "Forced expression of SCP2 in PA cells promoted tumor growth, and inhibition of SCP2 suppressed the proliferation of PA cells." (PMID 31519191, 2019). "Further IHC results indicated that the SCP2 protein was mainly localized in the cytoplasm of tumor cells and that HI-PA samples exhibited a higher staining intensity than LI-PA samples." (PMID 31519191, 2019). "Immunofluorescent staining of cryosections of mouse testis and of MA-10 mouse tumor Leydig cells showed that SCPX and SCP2 are present in both mouse testicular interstitial tissue and in MA-10 cells." (PMID 26901662, 2016). "On the other hand, we transfected SCp2 non-tumor epithelial mammary cells with an expression vector containing the full length cDNA sequence of Runx1 down-stream of a CMV-promoter." (PMID 26735887, 2016). "On day 14, these tumors weighed less and were smaller when treated with ZOL compared to vehicle-treated SCP2 plus Hs27a tumors (tumor weight: 23.0 ± 8.6 mg vs 42.7 ± 17.7 mg P < 0.01, size: 32.4 ± 19.8 mm3vs 55.5 ± 21.7 mm3P < 0.05)." (PMID 26203666, 2015). "The log2(Tumor/Healthy) analysis showed SCP2 is overexpressed almost two-fold in tumor cells." (PMID 39038933, 2024). "As indicated by previous research, SCP2 is able to regulate angiogenesis and tumour migration." (PMID 34541823, 2021). "Recent evidence supports an oncogenic role of SCP2 in tumor." (PMID 31519191, 2019). "Tumor proliferation and invasion are closely related, thus, we further investigated whether SCP2 could affect PA cell invasion." (PMID 31519191, 2019). "Notably, SCP2 is capable of regulating angiogenesis and tumour migration." (PMID 34541823, 2021). "In vivo, SCP2 overexpression and high cholesterol diet could promote tumor growth." (PMID 31519191, 2019). "However, whether SCP2 affects tumor progression by regulating cholesterol metabolism remains unknown." (PMID 31519191, 2019). "Both SCP2 overexpression and HCD feeding promoted tumor growth, while ezetimibe and vismodegib inhibited tumor growth in vivo." (PMID 31519191, 2019). "Conversely, SCP2, ALDH3A2, and PRKAA2 were found to be expressed at lower levels in tumor tissues." (PMID 40271062, 2025). "In contrast, tumors derived from animals transplanted with p21-depleted SCP2 cells formed a well-encapsulated tumor mass that did not invade the surrounding tissues, strongly suggesting that p21 plays an important role in tumor invasion." (PMID 22995475, 2012). "In this work, we also found a slight decrease in the protein levels of AKT in response to LY294002 in C4-HI tumor cells but not in non-malignant Scp2 cells." (PMID 20520761, 2010). "None of the animals in which parental or p21-depleted SCP2 cells (eight per group) were injected into the mammary fat pad developed any bone lesions after two months, the date at which mice had to be sacrificed due to the tumor size." (PMID 22995475, 2012).
tumor (continued). "Whether SCg6 cells result in the tumor or induce transformation in epithelial cells is not yet clear; however, the induction of a spontaneous inflammatory response in SCp2 cocultured with SCg6 may be related to the predicate of chronic inflammation leading to cancer in epithelial tissues." (PMID 21118556, 2010).
cancer (12 papers, 2010 to 2025). A tumor composed of atypical neoplastic, often pleomorphic cells that invade other tissues. "Previous studies have explored the association between SCP2 and cancers." (PMID 40620061, 2025). "SCP2, ABCD3, and MICOS10 were significantly negatively correlated with cancer‐associated fibroblasts (CAFs)." (PMID 40620061, 2025). "We first investigated the effects of the COCO with MSC on the SCP2 gene expression in order to understand if cancer cells behave differently when in contact with bone microenvironment factors." (PMID 28758931, 2017). "We also found that the fatty acid transporter SCP2, which protects fatty acids from oxidation, is overexpressed in cancer." (PMID 25243088, 2014). "Both the SCP2 and BSG branches share the same CAV1 upstream regulators such as MAPK3, TNFRSF1B, and GNAI2, which have been implicated in cancer cells death pathways." (PMID 24949431, 2014). "The study of SCP2, ABCD3, MICOS10, GCDH, and MTRF1L genes' immune infiltration and cancer correlation in CRC offers a fresh perspective." (PMID 40620061, 2025). "Of note, this study for the first time revealed that the dysregulation of MAPK1, ACOX1, SCP2, and NLN is significantly correlated to the survival time in EC patients, whose functional importance had been implied in multiple cancer types." (PMID 34124063, 2021). "In order to understand if cancer cells and MSC affect bone microenvironment contributing to osteoclastogenesis, we dissected the contribution of either SCP2 or MSC on osteoclastogenesis, by supplementing pre-osteoclasts with the CM of either the SCP2 or the MSC mono-cultures and the SCP2-MSC COCO." (PMID 28758931, 2017).
infection (7 papers, 2013 to 2024). The state of being infected such as from the introduction of a foreign agent such as serum, vaccine, antigenic substance or organism. "The peroxisomal sterol carrier protein (Scp2) acts as a virulence factor essential for efficient host infection." (PMID 30678160, 2019). "It was hypothesized that Scp2 might influence the membrane lipid composition and, therefore, the infection process." (PMID 30678160, 2019). "At 5 days post-infection, viral yields were reduced by at least 10,000-fold in cells expressing SCP1, whereas no significant reduction was observed in cells expressing SCP2 or TK1." (PMID 23966856, 2013).
connective tissue diseases (1 paper, 2021). "Notably, SCP2 exerts function on vascular inflammation of systemic connective tissue diseases in rats." (PMID 34541823, 2021).
metabolic disorder (1 paper, 2014). "Our results indicate that PBMCs from patients with stable COPD or AECOPD had downregulated SCP2, which might point to severe metabolic disorder and thus that SCP2 downregulation might contribute to one of the common comorbidities of COPD." (PMID 25407108, 2014).
SCP2 also shares sentences with these, for which no sentence is quoted: Allergy (13 papers); anaphylaxis (8); food allergy (7); Azoospermia (3); cerebellar ataxia (3); Refsum disease (3); fungal infection (2); hyperglycaemia (2); peanut allergy (2); peripheral neuropathy (2); peroxisomal disorders (2); adenocarcinoma (1); Adult onset (1); Alzheimer disease (1); angioedema (1); asthma (1); Ataxia (1); Autosomal recessive spastic paraplegia type 46 (1); cervical carcinoma (1); cervical dystonia (1); cholestasis (1); clear cell renal cell carcinoma (1); contact urticaria (1); development delay (1); diabetic (1); glioblastoma (1); heart disease (1); Hypercholesterolemia (1); Hyperinsulinemia (1); hyperlipidemia (1).
A further 21 diseases each share a sentence with SCP2 in 1 paper.